IL1B (interleukin 1 beta)
Diseases named in the same sentence as IL1B in open-access papers (continued):
Sharing a sentence is not in itself a finding about the gene and the disease.
colitis (continued). "Exposure to IS alone significantly caused colitis: It induced colon shortening, colonic myeloperoxidase activity, proinflammatory cytokine IL-6 and IL-1β expression, and NF-κB activation, and COX-2 expression." (PMID 30979031, 2019). "Here we demonstrate that epithelial damage and innate immune cell infiltration into the colon in acute TNBS colitis is associated with increased concentrations of the key innate immune cytokine IL-1β and pronounced inhibitory effects on colonic motor activity." (PMID 29933379, 2018). "Concomitantly, expression of Il6, Tnf and Il1β were reduced in colitis colons of CCR-6-deficient mice." (PMID 29695802, 2018). "We observed increased IL-1β and IL-6 expressions in Rev-erbα-deficient mice at early stage of colitis (2 days of DSS feeding)." (PMID 30315268, 2018). "Yet another experimental model of colitis where IL-10-deficiency facilitates IL-1β proinflammatory effects comes somewhat unexpectantly from studies of TLR5-deficient mice." (PMID 30455704, 2018). "In a recent study, adiponectin-deficient mice treated with DSS exhibited more severe colitis accompanied by an increased presence of activated B cells, pro-inflammatory cytokines such as IL-1β, IL-4, and IL-6 and increased STAT3 signaling in the colon." (PMID 30369924, 2018). "Body weight loss in colitis and colitis-induced expression of Il6, Tnf, Il1β and Il10 were reduced in JHT mice." (PMID 29695802, 2018). "Exacerbated expression of IL-1β is associated with the development of IBDs such as colitis, and pharmacological neutralization of these cytokines reduces the severity of colitis." (PMID 29621237, 2018). "Further studies have demonstrated that Nlrp1b deficiency in mice was associated with reduced colonic levels of Il-18 and Il-1β with a concomitant increased colitis susceptibility and CAC development upon DSS- and AOM-DSS treatment." (PMID 29868004, 2018). "Reconstitution of HK-deficient mice through intravenous injection of HK recovered their susceptibility to DSS-induced colitis, increased IL-1β levels in the colon tissue and bradykinin concentrations in plasma." (PMID 29467753, 2018). "First, IL-1β was the primary inflammatory cytokine altered the most in Rev-erbα-deficient mice at the early phase of DSS-colitis." (PMID 30315268, 2018). "Anomalous expression of proinflammatory cytokines, particularly IL-1β, has been shown to be associated with colitis." (PMID 29621237, 2018). "This corroborates another study that has reported that AIM2 protein acts independently of the inflammasome and IL-1β in colitis-associated colon cancer." (PMID 29216217, 2017). "Increased pro-inflammatory cytokine production is a hallmark of DSS-induced colitis and among these cytokines, IL-1β plays an important role in intestinal inflammation." (PMID 28380426, 2017). "In comparison, IL-1β, produced mostly by myeloid cells, promotes healing and repair in colonic tissue; IL-1β deficient mice show more severe colitis with failure of repair mechanisms." (PMID 28288653, 2017). "On the other hand, induction of colitis evidently upregulated IL-1β, a hallmark cytokine of inflammasome activation, and it was suppressed in fasted mice, together with IL-17." (PMID 28955126, 2017). "Wild-type mice that received CD2–Tff2 bone marrow suffered the mildest colitis, while recipients of Tff2-null bone marrow had slightly more severe disease (measured by weight loss, spleen size, colonic shortening and colonic IL-1β expression)." (PMID 26841680, 2016). "The loss of Adamdec1 rendered mice more susceptible to the induction of bacterial and chemical induced colitis, as evidenced by increased neutrophil infiltration, greater IL-6 and IL-1β secretion, more weight loss and increased mortality." (PMID 27226416, 2016). "Induction of colitis caused more than 8-fold increase in concentration of IL-1β and more than 6-fold increase in concentration of TNF-α in colonic mucosa." (PMID 27433160, 2016).
colitis (continued). "While IL-1β blockage improves intestinal inflammation in different animal colitis models, another study showed that genetic deficiency of IL-1β leads to increased susceptibility to experimental colitis." (PMID 27034589, 2016). "Blimp-1 was also shown to participate in the development of colitis; its deficiency in dendritic cells induces increased production of IL-6 and IL-1β upon MDP stimulation, and this phenotype is obvious in colonic DCs but not in BMDCs." (PMID 27105524, 2016). "Neutrophil infiltration during colitis-associated CRC is well appreciated to drive IL-1β release in the tumor microenvironment, another strong activator of NF-κB in IECs and tumor cells." (PMID 27344176, 2016). "LJE alone caused a significant improvement of colitis signs such as colon length, histological score, and IL-1β and IL-6 production." (PMID 24948848, 2014). "For example, the caspase-1-deficient mouse is resistant to colitis but the IL-1β-deficient mouse is susceptible in the same disease model." (PMID 24115947, 2013). "In C57BL/6 mice, the transition from day 7 to 12 was characterised by high diarrhoea scores, increased weight loss, increased macroscopical signs of colitis and peak colon levels of IL-1β, CCL2, CXCL2/3 and CCL4." (PMID 22279558, 2012). "In contrast, hFcγR mice given IgG from patients with colitis developed colon inflammation marked by a significant increase in submucosal lymphocyte infiltration, goblet cell loss, and circulating cytokines, including IL-1β, IL-17a, and IL-22." (PMID 42282671, 2026). "Regarding pro-inflammatory cytokines, colitis caused a significant increase of IL-1α and IL-1β in both Mcpt-4fl/fl and Mcpt-4ΔCre mice, with Mcpt-4 deficiency promoting higher production of IL-1α and IL-1β." (PMID 40697820, 2025). "Notably, in the mouse mastitis model, mastitis was associated with colitis and systemic inflammatory response, as evidenced by elevated IL‐6, TNFα, and IL‐1β levels in circulation and colonic tissues (P < 0.01)." (PMID 40552401, 2025). "Indeed, sorbitol treatment leads to a higher proportion of M1 macrophages in the colon, worsening colitis, which is reversed in interleukin-1β (IL-1β)-deficient mice and mitigated with antibiotic treatment." (PMID 40678521, 2025). "Further studies reveal that the toll-like receptor 2/4 (TLR2/4)-NF-κB-NOD-like receptor thermal protein domain associated protein 3 (NLRP3) axis exacerbates colitis by inducing macrophage pyroptosis and IL-1β secretion, amplifying intestinal inflammation and barrier dysfunction." (PMID 41030455, 2025). "The findings indicated that curcumin effectively mitigated weight loss and colon shortening caused by colitis, enhanced the expression of anti-inflammatory factor IL-10 mRNA (p < 0.05), and suppressed the expression of pro-inflammatory factors (IL-1β, IL-6, and TNF-α mRNA; p < 0.05)." (PMID 40724653, 2025). "In particular, IL-1β plays a central role in mediating inflammatory responses, and it was found that blocking IL-1β activity significantly reduced mucosal damage and tumor formation in a colitis-associated CRC (CAC) mouse model." (PMID 38338927, 2024). "Notably, pduC-encoding AIEC is expanded in CD patients and induces colitis through IL-1β produced by CX3C motif chemokine receptor 1 (CX3CR1)+ mononuclear phagocyte." (PMID 38443988, 2024). "This defect in Il-22 expression, a cytokine known to regulate mucosal wound healing, associated with the increased expression of the pro-inflammatory cytokines Il-1β and Tnf-α, may play a role in the higher colitis susceptibility of GF Card9−/− mice." (PMID 38649950, 2024). "On the other hand, the pathogenic transformation of CD4+ T cells into GM-CSF-producing T cells in vivo, triggered by antigen presentation by tissue macrophages and the production of IL1α and IL1β associated with the inflammasome, facilitates the promotion of colitis and CAC." (PMID 38892354, 2024).
colitis (continued). "To further understand the protective efficacy of PS, we analyzed the content of colitis-associated inflammatory cytokines and found that pretreatment with PS reduced the levels of pro-inflammatory cytokines, such as IL-1β, TNF-α, and IL-6, while increased anti-inflammatory TGF-β1 cytokine levels." (PMID 37447380, 2023). "Colitis-associated myeloid cells have higher expression of genes involved in innate inflammatory pathways, suggesting that pathology is driven by inflammasome activation and production of IL-1β, IL-6, and TNFα." (PMID 37461742, 2023). "Earlier reports also revealed that blocking TNF-α, IL-1β, or IL-6 caused an anti-colitis effect." (PMID 37509556, 2023). "Importantly, gene expression levels of Lcn2, a biomarker of intestinal inflammation released by immune cells, and Il1b, the potent pro-inflammatory cytokine induced during colitis, were highly affected by MCJ deficiency when mice were treated with DSS." (PMID 35705557, 2022). "In a colitis-associated colon cancer mouse model, L. bulgaricus decreased intestinal inflammation and reduced tumour levels of IL-1β, IL-6, IL-17, IL-23 and TNF-α; L. acidophilus, L. rhamnosus and B. bifidum also reduced TNF-α and increased IL-10 in the colon of this mouse type." (PMID 35408849, 2022). "Mice deficient in IL-1β exhibited more aggressive intestinal inflammation compared to controls, suggesting a potential protective effect of IL-1β; Exogenous IL-1β is protective against acute colitis in Gsdmd−/− mice." (PMID 35677444, 2022). "They found that the hyperactive NLRP3 inflammasome, associated with local over-production of IL-1β, could maintain gut homeostasis resulting in strong resistance to experimental colitis." (PMID 34692718, 2021). "In addition, Il1b−/− mice were protected against DSS-induced colitis and presented decreased body weight loss and disease activity index determined by stool consistency and hemoccult." (PMID 33578830, 2021). "In a TPH1 knock out (TPH1(−/−)) colitis mice model, that lack 5-HT produced by ECs, it was found that macrophage infiltration, IL-1β, IL-6, and TNFα production and colitis-associated colonic tissue damage were significantly reduced compared to the control (TPH1(+/+)) mice." (PMID 33807994, 2021). "Decreasing levels of IL-6 and IL-1β have also been associated with the treatment of colitis." (PMID 33748287, 2021). "IL-1β is known to stimulate diarrhea, immune cell infiltration, and intestinal necrosis, and IL-6 reduction had shown to slow down the development of UC and colitis-associated colon cancer." (PMID 33041812, 2020). "We have previously reported that colitis associated colon carcinogenesis in AOM/DSS-treated mice model was induced more severely in male mice than female by way of the inflammatory mediators such as IL-1β and MPO30." (PMID 32704056, 2020). "Collectively, these data show that CD11c-restricted Mbd2 deficiency resulted in increased severity of experimental colitis, characterized by elevated infiltration of IL-1β producing neutrophils and monocytes but equivalent numbers of LP T cells and colon IFN-γ transcript." (PMID 32117307, 2020). "In addition, key cytokines associated with colitis (IL-1β, IL-6, and IL-17A) were significantly suppressed, following treatment with M2b macrophage exosomes." (PMID 31749791, 2019). "We found that there were 15 analytes upregulated in both DSS and C. rodentium colitis, including innate immune cell-associated cytokines (G-CSF, IL-1β, TNF-α, LIF, and IL-6), chemokines (CCL2, CCL5, CCL11, CXCL2, CXCL8, CXCL9, MIP-1α, and MIP-1β), and Th1 (IFN-γ) and Th17 (IL-17) cytokines." (PMID 30972302, 2019). "The role of IL-1β in promoting intestinal inflammation has also been confirmed in infection studies, as blocking IL-1β ameliorated pathology in both Clostridium difficile-associated colitis and Salmonella Typhimurium-induced enteritis." (PMID 28979266, 2017).
colitis (continued). "Also, mice deficient in NLRP3 were more susceptible to either DSS or TNBS-induced colitis and exhibited decreased IL-1β as well as decreased beta-defensins." (PMID 24115947, 2013). "Finally, the pro-inflammatory cytokines TNF-α, IFN-γ, IL-1β and IL-6, and anti-inflammatory cytokine IL-10 have been implicated in experimental and human colitis." (PMID 22844504, 2012). "Furthermore, the upsurge in IL-1β within colitis contexts may also be linked to the stimulation of the NF-κB signaling pathway, a crucial transcription factor involved in orchestrating inflammatory responses through the modulation of numerous cellular genes." (PMID 40001993, 2025). "Neutrophil-depleted mice developed more severe colitis than controls, characterized by significant weight loss, aggravated histological lesions, impaired mucosal barrier function, and expression of proinflammatory cytokines (e.g., IL-1β, IL-17A, IFN-γ and TNF-α) in the colon tissues." (PMID 36729914, 2023). "Despite the DSS-colitis is caused through the toxic damage of the intestinal and colonic epithelial cells, the inflammatory reactions ensue after the proinflammatory cytokines (Il-1β, Il-6, TNFα, and INFγ) production by tissue macrophages that seems to play an essential role in the disease process." (PMID 36384756, 2022). "plantarum Q7 (LpQ7-MVs) were administered to DSS-induced colitis mice, evidenced by the amelioration in the colonic histological damage, which was associated with the downregulation in the production and release of pro-inflammatory cytokines (IL-6, IL-1β, IL-2 and TNF-α)." (PMID 36558455, 2022). "Moreover, inhibition of IL-1β rescued mice from increased colitis in PTPN2-deficient mice." (PMID 33808793, 2021). "Thus, CGD-associated colitis can be blocked by regulating IL-1β signaling." (PMID 33808793, 2021). "This hypothesis was proven true by administering mice MCC950, a specific inhibitor of the NLRP3 inflammasome, as MCC950 administration reduced the severity of colitis in Slco2a1-deficient mice via suppressing the expression of mature IL-1β and cleaved caspase-1." (PMID 32184453, 2020). "Similarly, Aim2−/− mice showed an impaired Il-1β and Il-18 synthesis associated with an overgrowth of colonic E. coli and an increased risk of developing colitis which may be counteracted by Il-18 infusion." (PMID 29868004, 2018). "We, amongst others, have recently demonstrated that the acute stage of TNBS colitis is associated with activation of innate immune responses, which results in infiltration of macrophages into the colon and increased concentrations of key innate cytokines including IL-1β." (PMID 29933379, 2018). "Intestinal damage secondary to murine DSS-induced colitis, ischemia/reperfusion injury total body irradiation and infectious colitis are all associated with a robust inflammatory response, and specifically, with robust expression of the inflammatory cytokines, IL1β, IL10, and TNFα." (PMID 28257503, 2017). "IEC SIRT3 deficiency enhances the production of IL-1β and promotes local TH1 and CTL differentiation in limiting colorectal cancer growth and aggravating colitis." (PMID 41487042, 2026). "In the cohousing experiment with Il1β−/− mice, wild-type mice showed greater susceptibility to DSS-induced colitis." (PMID 40678521, 2025). "In the context of colitis, a large number of macrophages accumulate in the lamina propria near the epithelium and overexpress pro-inflammatory cytokines such as IL-1β and TNF-α, indicating macrophage polarization." (PMID 41008172, 2025). "The present investigation observed notably elevated pro-inflammatory cytokine levels (TNF-α, IL-6, and IL-1β) in the colon of mice with DSS-induced colitis." (PMID 39699220, 2025). "The results of this study indicate that Pediococcus pentosaceus M6 can reduce the expression of IL-6 and IL-1β and increase the expression of IL-10, suggesting that Pediococcus pentosaceus M6 can effectively alleviate the progression of colitis in mice." (PMID 40431130, 2025).
colitis (continued). "Reduced editing and Flna expression levels were associated with an increased expression of classical proinflammatory cytokines and chemokines like Il1b, Cxcl1, or Il6, which are typically induced during colitis." (PMID 40471139, 2025). "In female rats, estrogen and progesterone reduced the production of macrophage migration inhibitory factor (MIF), which promotes tumor necrosis factor (TNF)-alpha and interleukin-1β (IL-1β) expression in early colitis." (PMID 40636118, 2025). "Atranorin administration protected against NLRP3 inflammasome-driven diseases and ameliorated colitis in vivo by improving epithelial barrier function and reducing IL-1β and IL-18 production." (PMID 40869366, 2025). "To assess the effect of FBT on the inflammatory response in colitis mice, we used ELISA kits to detect the levels of inflammatory factors IL-1β, IL-6, and TNF-α in the serum." (PMID 40238292, 2025). "The RT-qPCR results demonstrated elevated expression of Il-1β and Tnf-α mRNA in the colitis rats compared to the controls." (PMID 40018047, 2025). "Inflammasome activation and release of IL-1β is known to be an important pathological factor that accelerates the progression of DSS-induced colitis." (PMID 39899477, 2025). "This was accompanied by a prominent increase in colonic mRNA of the proinflammatory cytokines Il‐1β, Tnfa, and Il‐6 as well as the interferon‐stimulated gene, Ifit2, in mice with colitis compared to the healthy controls." (PMID 40018982, 2025). "Another study found that FOS lowers colitis and levels of the pro-inflammatory cytokine IL-1β in rats given rat chow." (PMID 40521353, 2025). "Passiflora edulis leaf aqueous extract lowered the pro‐inflammatory cytokines TNF‐a and IL‐1b in a rat model of colitis induced by 2,4,6‐trinitrobenzene sulfonic acid." (PMID 40625630, 2025). "Bulk RNA sequencing of colon tissues from FLNAR and FLNAQ animals on day 10 of DSS-induced colitis (the peak of disease) confirmed that FLNAR mice had less inflammation as indicated by a reduced expression of inflammatory genes (Il1b, Cxcl3, Cxcl2, or Trem1)." (PMID 40471139, 2025). "We observed that Areg−/− mice exhibited more severe colitis than WT mice, as evidenced by higher intestinal inflammation score and elevated expression levels of inflammatory mediators like IL-1β and TNF-α." (PMID 40247299, 2025). "In the betanin supplementation groups, malondialdehyde, myeloperoxidase, TNF-α, IL-1β, mucosal damage, and cell infiltration scores were lower than in the colitis group, while GPx levels were higher." (PMID 41515203, 2025). "In this study, DSS-induced colitis in mice was associated with significant upregulation of IL-6, TNF-α, and IL-1β." (PMID 41257293, 2025). "In the CSA cohort, vehicle-treated colitis mice exhibited marked elevations in IL-6 (p < 0.001), IL-1β (p < 0.0001), MCP-1 (p < 0.0001), and TNF-α (p < 0.0001) compared to healthy controls." (PMID 40869234, 2025). "Studies in murine DSS-induced colitis models show that CST treatment significantly reduced colonic levels of pro-inflammatory cytokines such as IL-1β, IL-6, IL-18, and TNF." (PMID 40370467, 2025). "To guarantee that PTX3/IL-1β signaling is involved in human colitis or leukemia, we searched publicly available datasets of bulk RNA-seq or scRNA-seq and compared their expression between the disease group and healthy controls." (PMID 40230417, 2025). "In DSS-induced mouse colitis models, inhibition of mRNA expression of caspase-1 or IL-1β gene can alleviate colitis." (PMID 40362256, 2025). "By stopping the production of TNF-α, IL-6, and IL-1β in animals with DSS-induced colitis, AVE was shown to have anti-inflammatory effects in this study." (PMID 40699788, 2025). "Inflammation is well‐established in many types of kidney damage and here, several of the kidney markers altered by colitis, i.e., Il‐1β, c‐Jun, and NF‐κB p65, are related to inflammation." (PMID 40018982, 2025).